STRA6 (signaling receptor and transporter of retinol STRA6)
Diseases named in the same sentence as STRA6 in open-access papers (continued):
Sharing a sentence is not in itself a finding about the gene and the disease.
diabetes (6 papers, 2010 to 2023). "In conclusion, our studies in WT and Stra6-/- mice support the association between diabetes and vitamin A metabolism." (PMID 35740038, 2022). "On the other hand, the association between STRA6 polymorphisms and type 2 diabetes mellitus (DM2) has been studied in Indian and Chinese populations." (PMID 33324556, 2020). "Percentage prevalence of diabetes increased with increase in number of risk alleles when analyzed with sentinel SNPs in STRA6 (rs736118), RBP4 (rs3758539) and GLUT4 (rs5435)." (PMID 20625434, 2010). "In summary, our study found SNP rs736118 of STRA6 was associated with type 2 diabetes mellitus and protected human against T2DM, but the interaction between STRA6 gene and drinking history, T2DM family history, and overweight easily leads to the occurrence of T2DM." (PMID 27446956, 2016). "Remarkably, short-term diabetes had a positive effect on the ocular retinoid phenotype, as seen by a slight but significant increase in the retinoid concentration in diabetic Stra6-/- mice." (PMID 35740038, 2022). "To confirm diabetes in WT and Stra6-/- mice after 30 weeks, we again determined the HbA1c concentration in the serum of the remaining mice." (PMID 35740038, 2022). "The elevated retinoid concentrations in the eyes of the diabetic Stra6-/- mice are likely explained by the effects of diabetes on lipoprotein metabolism." (PMID 35740038, 2022). "To analyze a putative connection between vitamin A metabolism and diabetes, we examined the changes enforced by diabetes on this metabolism in WT mice and Stra6-/- mice." (PMID 35740038, 2022). "This outcome confirmed that we successfully induced diabetes in Stra6-/- and WT mice." (PMID 35740038, 2022). "Stimulated by retinoic acid gene homolog 6 (STRA6) and retinoic acid receptor responder 2 (RARRES2) are candidate genes involved in the pathogenesis of type 2 diabetes mellitus (T2DM)." (PMID 27446956, 2016). "In Stra6-/- mice, diabetes increased total ocular retinoid concentration but not oxidative stress in the retina when compared to non-diabetic Stra6-/- mice." (PMID 35740038, 2022).
diaphragmatic hernia (6 papers, 2013 to 2022). A congenital or acquired weakness or opening in the diaphragm which allows abdominal contents to protrude into the chest cavity; congenital diaphragmatic hernias are caused when the embryonic diaphragm fails to fuse. "STRA6 mutations causing deficient RA signaling can contribute to a spectrum of developmental abnormalities, including micro/anophthalmia, heart defects, pulmonary dysplasia, and diaphragmatic hernia." (PMID 35682657, 2022).
breast carcinoma (5 papers, 2020 to 2025). "Stra6 (for all-trans-retinol uptake) mRNA was upregulated in human breast cancer as compared to normal breast tissue and elevated in colorectal cancer, and undetectable in normal colon tissue." (PMID 36768694, 2023). "Stra6 over-expression also promoted the oncogenic potential of MCF-7 breast cancer cells." (PMID 36768694, 2023). "In some tissues, including breast cancer, the retinol/RBP4 complex can be internalized into the cell via a plasma membrane protein known as STRA6 (Signaling Receptor And Transporter of Retinol STRA6)." (PMID 38360674, 2024).
gastric cancer (5 papers, 2015 to 2024). A primary or metastatic malignant neoplasm involving the stomach. "Recent research has uncovered the involvement of STRA6 in tumor initiation and progression as well as that STRA6 is highly expressed in various tumor cells, such as thyroid cancer, colorectal cancer, lung cancer, gastric cancer, etc., and is associated with prognosis." (PMID 38398143, 2024). "In gastric cancer (GC), STRA6 has been found to be upregulated, and its knockdown inhibited Wnt/β catenin signalling." (PMID 34785649, 2021). "However, the biological roles of STRA6 in gastric cancer (GC) remain unknown." (PMID 31694721, 2019). "However, some genes such as HOXC9, FNDC1, STRA6, KCNE2, PGA3 and KCNJ16 haven’t been reported in gastric cancer and their roles remain unknown." (PMID 25928635, 2015).
Obesity (5 papers, 2017 to 2026). Accumulation of substantial excess body fat. "The fact that the major transcription factors involved in de novo lipogenesis are regulated by retinol via STRA6 suggests that steatosis arising from diet-induced obesity might be caused by the hepatocyte accumulation of retinol which was released via STRA6 from activated HSC." (PMID 33407858, 2021). "Nevertheless, STRA6 expression is reduced in perigonadal AT and in the stromovascular fraction of the subcutaneous and perigonadal AT in mice models of diet-induced and genetically induced obesity, which possibly limits the anti-adipogenic potential of the RBP4/STRA6 axis." (PMID 35406450, 2022). "In metabolic diseases such as obesity and type 2 diabetes, elevated RBP4 levels engage endothelial STRA6, initiating a signaling cascade independent of retinol nuclear activity." (PMID 41782879, 2026).
Type 2 Diabetes (5 papers, 2010 to 2026). "We report for the first time that genetic variants in STRA6 are significantly associated with type 2 diabetes." (PMID 20625434, 2010). "In this study, SNPs in GLUT4, RBP4 and STRA6 were analyzed for association with type 2 diabetes in a South Indian population." (PMID 20625434, 2010). "In conclusion, we analyzed SNPs in three candidate genes namely, GLUT4, RBP4 and STRA6 for association with type 2 diabetes." (PMID 20625434, 2010). "Identification of STRA6 as a cell surface receptor for RBP4 provides further link in this axis and hence we analyzed SNPs in these three genes for association with type 2 diabetes in a South Indian population." (PMID 20625434, 2010). "The role of STRA6 in type 2 diabetes and its regulation by TCF4 are currently under investigation in our laboratory." (PMID 20625434, 2010). "Our gene-gene interaction data reveals that when the sentinel SNPs in STRA6, RBP4 and GLUT4 are combined together they increase the prevalence of type 2 diabetes with increase in the number of risk alleles." (PMID 20625434, 2010). "SNPs in STRA6, gene coding the cell surface receptor for RBP4, were significantly associated with type 2 diabetes and further genetic and functional studies are required to understand and ascertain its role in the manifestation of type 2 diabetes." (PMID 20625434, 2010). "None of the GWAS study in other populations identified STRA6 as a susceptibility loci for type 2 diabetes." (PMID 20625434, 2010). "We provide evidence supporting a novel genetic role for the STRA6 loci in type 2 diabetes." (PMID 20625434, 2010).
ovarian carcinoma (4 papers, 2014 to 2025). A malignant neoplasm originating from the surface ovarian epithelium. "A study found that the expression of IRF1 and STRA6 was markedly upregulated in the ovarian cancer cell line HEY." (PMID 41465326, 2025). "STRA6 markedly decreased the invasion and migration ability of the ovarian cancer cell line HEY." (PMID 41465326, 2025). "We tested the expression level of STRA6 in ovarian cancer cells with qRT-PCR." (PMID 29642915, 2018). "STRA6 expressed in the ovarian cancer cell lines, although its level was not affected by RBP4." (PMID 29642915, 2018).
colorectal cancer (3 papers, 2017 to 2024). A primary or metastatic malignant neoplasm that affects the colon or rectum. "Stra6 was critical for tumour formation by colorectal cancer cells because of stable down-regulation within the human primary adenocarcinoma SW480 cells by means of an shRNA vector, markedly suppressed tumour formation in athymic nude mice." (PMID 36768694, 2023). "HCT116 human colorectal cancer cells that stably over-expressed Stra6 developed substantially larger tumours than parental cells in athymic nude mice." (PMID 36768694, 2023). "Indeed, our data show that STRA6 and RBP4 are upregulated in colorectal cancers compared with normal colon, and also in more advanced disease with worse prognosis." (PMID 28689994, 2017).
lung carcinoma (3 papers, 2020 to 2025). "Furthermore, information regarding STRA6 genetic variability and its relationship with lung cancer remains unexplored." (PMID 33324556, 2020).
lung hypoplasia (3 papers, 2014 to 2021). "For example, miR-455-5p upregulation influences retinol absorption in a lung hypoplasia model by regulating STRA6." (PMID 34784837, 2021).
non-small cell lung carcinoma (3 papers, 2020 to 2022). A group of at least three distinct histological types of lung cancer, including non-small cell squamous cell carcinoma, adenocarcinoma, and large cell carcinoma. "Further, polymorphisms in the STRA6 gene are associated with increased incidences and aggressive courses of non-small cell lung cancer." (PMID 35323693, 2022). "Moreover, STRA6 polymorphisms are associated with epidermal growth factor receptor (EGFR) mutations and might be therapeutic targets for patients with non-small cell lung cancer." (PMID 35874675, 2022).
psoriasis (3 papers, 2020 to 2022). An autoimmune condition characterized by red, well-delineated plaques with silvery scales that are usually on the extensor surfaces and scalp. "Other transcripts such as Fbp1 are important in the Nrf2 stress pathway, Stra6 is involved in vitamin A transport in a murine psoriasis model, and 2 transmembrane proteases (Tmprss11e/f) are involved in skin barrier function." (PMID 34823472, 2021). "Serum STRA6 levels in psoriasis patients have rarely been studied." (PMID 31956331, 2020). "RBP4, STRA6, and the transformation from retinol to retinoic acid were upregulated, which may be part of the mechanism of psoriasis skin lesion formation." (PMID 31956331, 2020). "The aims of the present study were to create a psoriasis mouse model and to use it to detect the levels of RBP4, STRA6, retinol, and other vitamin A-related molecules in the circulation and in skin lesions." (PMID 31956331, 2020). "Changes in psoriasis patients of the levels of retinol-binding protein 4 (RBP4), a carrier of retinol (vitamin A); transmembrane protein stimulated by retinoic acid 6 (STRA6); and other retinol metabolic molecules have not yet been fully established." (PMID 31956331, 2020).
dyslipidemia (2 papers, 2016 to 2017). "In summary, this study reveals that electronegative L5 can cause kidney apoptosis and fibrosis via the suppression of STRA6 cascades, and implicates that STRA6 signaling may be involved in dyslipidemia-mediated kidney disease." (PMID 27256691, 2016).
endometriosis (2 papers, 2021 to 2024). The growth of functional endometrial tissue in anatomic sites outside the uterine body. "rs4244593 of PEMT-related polymorphism modulated the choline or phospholipids generation, inducing infertility of endometriosis women.STRA6 is vital for retinol binding protein, and retinol uptake into cells." (PMID 38844959, 2024). "Considering that RBP4 serves as a signaling molecule activating downstream pro-oncogenic signaling pathways after binding to the membrane receptor STRA6, the data of the present study seem to support the idea that ectopic endometrial cells can exhibit malignant biological behaviors in endometriosis." (PMID 34072419, 2021).
liver fibrosis (2 papers, 2019 to 2021). "Among the seven potential biomarkers FABP3, GALNT5, GPR84, ITGB6, MYEOV, PLEKHS1, and STRA6, we are particularly interested in GPR84 and STRA6 because they link to liver fibrosis that is a major risk factor in HCC and an independent risk factor of recurrence after hepatectomy." (PMID 31828095, 2019). "Here, we found that siRNA-mediated knock-down of Stra6 suppressed the early development of liver fibrosis in TAA-liver injury mouse model." (PMID 33407858, 2021). "Retinol from HSCs via STRA6 in response to injury with TIF1γ-reduction is taken up by hepatocytes via STRA6, leading to fat-deposition and damage, and liver fibrosis." (PMID 33407858, 2021). "The role of STRA6-mediated retinol transfer from HSCs to hepatocytes in liver fibrosis was demonstrated by in vivo experiments where blocking of STRA6 reduced fibrosis." (PMID 33407858, 2021). "Given our results indicating that STRA6 plays a role in promoting lipogenesis in hepatocytes via uptake of retinol released from HSC during fibrosis, we hypothesized that suppression of STRA6 would repress liver fibrosis." (PMID 33407858, 2021). "Notably, delivery using the vitamin A-liposome complex allowed specific targeting of the siRNA of STRA6 to HSCs, and could be used as a strategy to prevent the initial development of fat deposition and damage in hepatocytes and liver fibrosis by knocking down STRA6 in these cells." (PMID 33407858, 2021).
melanoma (2 papers, 2023 to 2025). A malignant, usually aggressive tumor composed of atypical, neoplastic melanocytes. "Notably, the expression of STRA6 was positively correlated with BRAF mutation in TC and melanoma." (PMID 36843593, 2023).
thyroid cancer (2 papers, 2023 to 2024). "Taken together, STRA6 is upregulated in thyroid cancer and exhibits extremely higher expression in BRAF-mutant PTC." (PMID 36843593, 2023). "STRA6 was upregulated in most cancers including thyroid carcinoma." (PMID 36843593, 2023).
thyroid tumor (2 papers, 2018 to 2023). A benign or malignant neoplasm affecting the thyroid gland. "Based on a public dataset GSE199023, zebrafish thyroid tumors transfected with BRAFV600E oncogenes showed higher expression of STRA6 as compared to those transfected with CCDC6-RET fusion." (PMID 36843593, 2023).
22q11.2 deletion syndrome (1 paper, 2024). 22q11.2 deletion syndrome (DS) is a chromosomal anomaly which causes a congenital malformation disorder whose common features include cardiac defects, palatal anomalies, facial dysmorphism, developmental delay and immune deficiency. "Notably, we also identified significant variants in the causative genes of rare neurodevelopmental disorders sharing comorbidities with FASD, including STRA6 (Matthew–Wood), SOX9 (Campomelic Dysplasia), FDG1 (Aarskog), and 22q11.2 deletion syndrome (TBX1)." (PMID 38785976, 2024).
Anosmia (1 paper, 2023). An inability to perceive odors. "Aerosolized retinoic acid may have an effective role in treating post-COVID-19 anosmia through upregulating ACE2 and STRA6 and regenerating OSNs expressing olfactory receptors." (PMID 37366867, 2023).
Blindness (1 paper, 2015). Blindness is the condition of lacking visual perception defined as a profound reduction in visual perception. "Similarly, STRA6 mutations cause severe developmental defects in humans, but STRA6 knockout mice, like RBP knockout mice, have only vision-specific phenotypes of blindness due to the lack of vitamin A." (PMID 26343735, 2015).
campomelic dysplasia (1 paper, 2024). "Potentially pathogenic variants were discovered in the FAS and pFAS groups, including those known to cause craniofacial malformations, such as SOX9 (Campomelic Dysplasia), STRA6 (Matthew–Wood), CHD7 (CHARGE), MID1 and MED15 (Opitz–Kaveggia syndrome), and several 22q11.2DS genes." (PMID 38785976, 2024).
cardiac hypertrophy (1 paper, 2023). "The BNP level, cardiac hypertrophy and interstitial fibrosis were also improved after administrated Stra6 siRNA in HFpEF after CKD mice." (PMID 37564202, 2023).
Cirrhosis (1 paper, 2021). A chronic disorder of the liver in which liver tissue becomes scarred and is partially replaced by regenerative nodules and fibrotic tissue resulting in loss of liver function. "In conclusion, fatty liver disease and cirrhosis in response to injury may be induced by complex interplay between HSCs and hepatocytes by transport of retinol between these cells through STRA6." (PMID 33407858, 2021).
congenital diaphragmatic hernia (1 paper, 2020). A posterolateral defect of the diaphragm that allows passage of abdominal viscera into the thorax, leading to respiratory insufficiency and persistent pulmonary hypertension with high mortality. "Consistent with these RA-mediated mechanisms, we note that human mutations in STRA6 cause syndromic congenital diaphragmatic hernia with both CHD and pancreatic anomalies." (PMID 33054971, 2020).
Donnai-Barrow syndrome (1 paper, 2016). Donnai-Barrow syndrome (DBS) is a rare, often severe, multiple congenital malformation syndrome with typical facial dysmorphism, ocular findings, hearing loss, agenesis of the corpus callosum, and variable intellectual disability. "Furthermore, resemblance of the phenotype of individuals with a STRA6 mutation (Mathew-Woods syndrome) with individuals with an LRP2 mutation (Donnai-Barrow syndrome) is obvious, as is the resemblance of a zebrafish model in which STRA6 function is disrupted with the Lrp2 knockout mouse." (PMID 26822476, 2016).
embryonal carcinoma (1 paper, 2018). A non-seminomatous malignant germ cell tumor characterized by the presence of large germ cells with abundant cytoplasm resembling epithelial cells, geographic necrosis, high mitotic activity, and pseudoglandular and pseudopapillary structures formation. "Stra6 was initially cloned from embryonal carcinoma (P19) cells." (PMID 30020971, 2018).
fatty liver disease (1 paper, 2021). A reversible condition wherein large vacuoles of triglyceride fat accumulate in liver cells via the process of steatosis. "Finally, SREBP1 induces a cluster of lipogenesis genes and fat deposition in hepatocytes, while STRA6 expression enhances uptake of retinol released from HSC and establishes the vicious cycle, leading fatty liver disease and liver cirrhosis." (PMID 33407858, 2021).
gestational diabetes (1 paper, 2021). Carbohydrate intolerance first diagnosed during pregnancy. "This study’s objective was to evaluate the placental expression and staining pattern of STRA6 and the expression pattern of some of the most relevant enzymes involved in the metabolic pathway of retinoids during gestational diabetes." (PMID 34945773, 2021). "The study’s objective was to assess placental STRA6 expression and staining pattern in human pregnancy complicated by gestational diabetes mellitus (GDM)." (PMID 34945773, 2021). "Our results highlight an increased expression of LRP1 and LPL in placentas of insulin-treated gestational diabetes and, in turn, an increase in the intracellular ROH apparatus by the non-STRA6 pathway." (PMID 34945773, 2021).
glomerulonephritis (1 paper, 2024). A renal disorder characterized by damage in the glomeruli. "In contrast, PEC-A1 had little Aldh1a2, Rdh10, Stra6 and Rbp1 expression in control mice and on day 1 of anti-GBM glomerulonephritis but had higher Rdh10 mRNA expression on day-5 compared to day-1 in anti-GBM glomerulonephritis." (PMID 39360029, 2024).
heart failure (1 paper, 2025). Inability of the heart to pump blood at an adequate rate to meet tissue metabolic requirements. "We hypothesized that Stra6 expression attenuates ischemic injury-induced heart failure following myocardial infarction (MI) by vitamin A-dependent mechanisms." (PMID 41035698, 2025).
hip osteoarthritis (1 paper, 2021). "The STRA6 gene has been associated with behavioral inhibitory control, as well as knee and hip osteoarthritis." (PMID 34603368, 2021).
Hyperglycemia (1 paper, 2018). An increased concentration of glucose in the blood. "This compound neutralized the hyperglycemia-elicited reduction of the retinoid visual cycle components of RPE65, LRAT, RDH5, CRBP, CRALBP, IRBP, and STRA6 in retina." (PMID 30096827, 2018).
Intellectual disability (1 paper, 2013). "The absence of any intellectual disability and the relatively mild pulmonary phenotype in the boy with a compound heterozygous mutation in STRA6 is interesting." (PMID 24498598, 2013).
intestinal tumors (1 paper, 2024). "In addition to serving as a carrier for retinol, STRA6 also acts as a cell surface signaling receptor for RBP4, influencing the occurrence of intestinal tumors and insulin secretion in pancreatic beta cells." (PMID 39518840, 2024).